COBL (cordon-bleu WH2 repeat protein)
Description:
Plays an important role in the reorganization of the actin cytoskeleton. Regulates neuron morphogenesis and increases branching of axons and dendrites. Regulates dendrite branching in Purkinje cells (By similarity). Binds to and sequesters actin monomers (G actin). Nucleates actin polymerization by assembling three actin monomers in cross-filament orientation and thereby promotes growth of actin filaments at the barbed end. Can also mediate actin depolymerization at barbed ends and severing of actin filaments. Promotes formation of cell ruffles.
Synonyms: KIAA0633
Tractability: Small molecule: a structure with a bound ligand is known. Antibody: UniProt places it where antibodies can reach, with medium confidence; its Gene Ontology location is reachable by antibodies, with medium confidence; the Human Protein Atlas places it where antibodies can reach. PROTAC: ubiquitination databases record sites on it; its protein half-life has been measured.
Gene: Protein-coding gene on chromosome 7 (51,016,211 to 51,317,187, reverse strand). Ensembl gene ENSG00000106078.
Subcellular location: Cell membrane; Cytoplasm, cytoskeleton; Cell projection, ruffle; Cytoplasm
Subcellular location (Human Protein Atlas): Cell Junctions; Plasma membrane
Gene Ontology:
Molecular function: protein binding; actin monomer binding; actin binding
Biological process: actin filament network formation; actin filament polymerization; collateral sprouting in absence of injury; digestive tract development; embryonic axis specification; floor plate development; liver development; neural tube closure; notochord development; positive regulation of dendrite development; somite specification; positive regulation of ruffle assembly
Cellular component: actin filament; axon; axonal growth cone; cell cortex; dendrite; dendritic growth cone; membrane; neuronal cell body; perinuclear region of cytoplasm; plasma membrane; ruffle; cytoplasm; cytoskeleton
Genetic constraint (gnomAD): Loss-of-function variants: 47 observed, 94.01 expected, observed/expected ratio (o/e) 0.5, 90% interval 0.4 to 0.64. The upper end of that interval is the gene's LOEUF score, 0.64, which puts it in group 2 of 6, group 1 being the genes least tolerant of losing a copy. Missense variants: 1,572 observed, 1,609.1 expected, observed/expected ratio (o/e) 0.98, 90% interval 0.94 to 1.02. Synonymous variants: 615 observed, 647.75 expected, observed/expected ratio (o/e) 0.95, 90% interval 0.89 to 1.01.
Homologues: Orthologues: chimpanzee COBL (98% identical), macaque COBL (93% identical), mouse Cobl (67% identical), rat Cobl (66% identical), dog COBL (63% identical), rabbit COBL (61% identical), guinea pig COBL (56% identical), tropical clawed frog cobl (32% identical), zebrafish cobl (28% identical). Paralogues in human: COBLL1 (19% identical).
Diseases named in the same sentence as COBL in open-access papers:
COBL is named in the same sentence as 25 diseases in open-access papers, as found by Europe PMC text mining. Sharing a sentence is not in itself a finding about the gene and the disease. The quoted sentences say what the papers report.
acute lymphoblastic leukemia (2 papers, 2016 to 2020). Leukemia with an acute onset, characterized by the presence of lymphoblasts in the bone marrow and the peripheral blood. "In acute lymphoblastic leukemia, COBL is a hotspot for IKZF1 deletions, and we will study the function of COBL in HNSCC in the future." (PMID 33614471, 2020). "Cordon-Bleu WH2 Repeat Protein (COBL) has been reported to play an important role in the reorganization of the actin cytoskeleton, and as a hotspot for IKZF1 deletions in acute lymphoblastic leukemia." (PMID 33614471, 2020).
COVID-19 (2 papers, 2023 to 2024). A disease caused by infection with severe acute respiratory syndrome coronavirus 2. "This in silico model predicted that five genes important for embryo implantation were affected by COVID-19 (down-regulation of COBL, GPX3 and SOCS3, and up-regulation of DOCK2 and SLC2A3)." (PMID 38372528, 2024). "COBL, GPX3 and SOCS3 were lower in the early and late secretory phase in women with COVID-19, whereas DOCK2 and SLC2A3 were unchanged." (PMID 38372528, 2024).
Obesity (2 papers, 2023). Accumulation of substantial excess body fat. "We detected significantly decreased expressions of COBL and MKX in subcutaneous AT samples of children with overweight and obesity compared to lean children, while the expression of MYOC was not altered with obesity." (PMID 36834493, 2023). "In summary, the expression of COBL, MKX and MYOC in AT is related to obesity, AT dysfunction, and the early signs of metabolic disease in children." (PMID 36834493, 2023). "Finally, we provide evidence that the expression of COBL, MKX and MYOC in subcutaneous AT is related to obesity, parameters of AT dysfunction, and the early signs of metabolic disease in children." (PMID 36834493, 2023). "Furthermore, COBL, MKX and MYOC expression in the subcutaneous AT of children is related to obesity and parameters of AT dysfunction and metabolic disease, such as adipocyte size, leptin levels and HOMA-IR." (PMID 36834493, 2023).
autoimmune disease (1 paper, 2018). A disorder resulting from loss of function or tissue destruction of an organ or multiple organs, arising from humoral or cellular immune responses of the individual to their own tissue constituents. "According to the GWAS Catalog and Immunobase, five of these shared loci (PADI4 at 1p36.13, NAB1 at 2q32.3, COBL at 7p12.1, CCL21 at 9p13.3, and GATA3 at 10p14) have been associated with a single autoimmune disease so far and thus they represent new pleiotropic loci in autoimmunity." (PMID 30572963, 2018).
glioblastoma (1 paper, 2022). The most malignant astrocytic tumor (WHO grade IV). "COBL is an actin nucleator involved in neurite outgrowth and of particular importance to proper cerebellum formation and ZEB2 is a zinc finger E-box binding transcription factor that plays a role in promoting migration and invasion of both adult and pediatric glioblastoma cells." (PMID 35590427, 2022).
Insulin resistance (1 paper, 2023). Increased resistance towards insulin, that is, diminished effectiveness of insulin in reducing blood glucose levels. "In addition to that, MKX but not COBL expression showed an inverse and BMI SDS-independent association with serum leptin levels (Radjusted = −0.168, padjusted = 0.028) and the insulin resistance marker HOMA-IR (Radjusted = −0.211, padjusted = 0.003)." (PMID 36834493, 2023).
panic disorder (1 paper, 2025). An anxiety disorder characterized by multiple unexpected panic attacks with persistent concern of recurring attacks. "These included: rs61739178 on chromosome 7, a missense variant in COBL with a reported role in neuron morphogenesis and axon/dendrite branching; and rs937529 on chromosome 12, upstream of panic disorder and spinocerebellar ataxia 23 gene TMEM132D." (PMID 39454566, 2025).
metabolic disease (1 paper, 2023). A congenital disorder (due to inherited enzyme abnormality) or acquired (due to failure of a metabolically important organ) disorder resulting from an abnormal metabolic process. "Furthermore, we provide evidence that the AT expression of COBL, MKX and MYOC is related to early signs of AT dysfunction and metabolic disease in children, indicating a potential role in the pathogenesis of these processes." (PMID 36834493, 2023).
COBL also shares sentences with these, for which no sentence is quoted: tumor (3 papers); Alzheimer disease (2); acute myeloid leukemia (1); albinism (1); Autoimmunity (1); cancer (1); cardiomyopathies (1); cardiovascular diseases (1); congenital stationary night blindness (1); glioma (1); lung squamous cell carcinoma (1); male infertility (1); melanoma (1); metastatic colorectal cancer (1); myelodysplastic syndrome (1); retinal disorder (1); Retinal dystrophy (1).